CCL1 (C-C motif chemokine ligand 1)
Diseases named in the same sentence as CCL1 in open-access papers (continued):
Sharing a sentence is not in itself a finding about the gene and the disease.
tumor (continued). "Overall, high levels of CCL1 and CCL18 in OC tissues can recruit CD4+CCR8+ Tregs into tumor tissues by recognizing CCR8 on cells and remodeling their inhibitory phenotypes, making them have stronger immunosuppressive phenotypes and proliferative abilities." (PMID 37950246, 2023). "Tregs are a crucial therapeutic target in the TME, they can be recruited to the TME by macrophages and tumor-derived factors such as CXCL12, CCL17 CCL22 and CCL1, thus suppressing the activation of T cells." (PMID 37656220, 2023). "The LKB1/AMPK/CCL-1/TAM axis leads to increased recruitment of monocytes at the tumor site, mainly some M2-like TAMs that play a pro-tumor function and promote the development of EC." (PMID 37810971, 2023). "Interacting with its cognate ligand CCL1, CCR8 induced Treg migration and retention in the tumor microenvironment." (PMID 36313180, 2022). "M-MDSCs are recruited to tumors via a CCL1, CCL5-induced chemokine cascade that is disseminated by tumor cells, and CCL3 produced by TAMs is retained in the primary tumor." (PMID 36686745, 2022). "We also identified unique signatures in tumour samples after VV-αCEA TCE treatment, including increased levels of CCL1, IFNγ, IL-1a, IL-1b, TIMP-1, and TREM-1." (PMID 36405739, 2022). "We found that the expressions of CCL1, FABP7, S100B, CTSW, and SEZ6 significantly decreased in the tumor tissue, the expression of CPLX2 and SPIB increased obviously in BC." (PMID 36581948, 2022). "In this context, in murine CRC tumor models, targeting CCR8+ Tregs through either anti-CCL1 neutralizing monoclonal antibody (mAb) or anti-CCR8 mAb drastically reduced the tumor infiltration by Tregs while robustly enhancing the antitumor immune response." (PMID 33924428, 2021). "It has been reported that CCL1, CCL2 and CCL21 affect tumor metastasis and progression through direct or indirect interactions with lymph nodes." (PMID 34321012, 2021). "CCL1 is another chemokine produced by the SCS LEC, which has been shown to control CCR8+ tumor cell entry and subsequent migration and colonization in the LN cortex." (PMID 28220121, 2017). "Our PCR array data showed that both M1-related genes (Ccl2, Ccl3, Ccl4, Ccl5, Il12b, Il1b and Ccl1) and M2-related genes (Il10, Tgfb2 and Il1rn) were significantly upregulated in NM11-shsST2 tumours compared with NM11-shCont tumours." (PMID 27882929, 2016). "We performed an in vitro chemotaxis assay with the chemokine ligands for CCR8 and CXCR4 (CCL1 and CXCL12) and observed these chemokines induced more efficient chemotaxis of tumor-infiltrating FoxP3+ T cells compared to their counterparts in lymph nodes." (PMID 22292042, 2012). "Furthermore, Lewis lung carcinoma-derived EVs stimulate lung fibroblasts to secrete excessive amounts of CCL1, an inflammatory cytokine, thereby activating CCL1-CCR8 axis in Tregs to promote their differentiation and pro-tumor function." (PMID 40908470, 2025). "Furthermore, certain chemokine family members such as CCL1, CCL2, and CCL5, which are highly expressed by CSCs in different cancer types, stimulate the infiltration of T-reg cells into the tumor microenvironment." (PMID 39671359, 2024). "They found that CCL1, secreted by activated T cells, provides positive feedback for the recruitment of CCR8 T cells to the tumor tissue, thereby increasing CAR-T cell infiltration and synergizing with DNR to mitigate tumor-derived immunosuppressive signals." (PMID 39350256, 2024). "In contrast, CCL1 in SOX2+ mouse breast cancer cell lines induced Treg cell migration, suggesting that multiple chemokines are involved in the recruitment of Treg cells to the tumour microenvironment." (PMID 39184916, 2024). "Additionally, TAMs overexpress CCL1, the ligand of CCR8 expressed on Tregs, to attract Tregs into the tumor area, inhibiting T cell immunity and promoting tumor growth." (PMID 38957393, 2024).
tumor (continued). "Additionally, the engagement of CCL1 with CCR8 expressed on tumor cells (e.g., melanoma, bladder cancer) promoted tumor cell proliferation, migration, and metastasis." (PMID 37108657, 2023). "Mechanisms that mediate this reduced recruitment of Tregs to HNSCC tumor microenvironments following BRB-E administration are still under active investigation, although chemokine-dependent infiltration via Ccl1, Ccl18, and Ccl22, and Vegfa-dependent recruitment are potential mechanisms." (PMID 36016924, 2022). "The mRNA expression levels of CCL1/5/7/11/17/19/20/22/25 chemokines were found to be elevated in primary tumors compared to normal specimens, while CCL2/3/4/8/13/14/15/16/18/21/23/24/28 were significantly downregulated in tumor samples." (PMID 35725915, 2022). "Interestingly, Sp1high LECs promoted the transactivation of C–C motif chemokine ligand 1 (CCL1) to facilitate TAM and tumour cell recruitment, thereby forming a positive feedback loop to strengthen the LVEM formation." (PMID 33484377, 2021). "Importantly, we confirmed that blockade of Sp1 or CCL1 prevented TAM proximity to LVs, thereby reducing tumour lymphangiogenesis and metastatic dissemination." (PMID 33484377, 2021). "M-MDSC and inflammatory monocytes are recruited to tumours through a CCL1, CCL2, and CCL5-induced chemokine cascade that is propagated by cancer cells and has been found to be retained within primary tumours by CCL3 produced via CCR-2 activated mechanism in metastasis-associated macrophages." (PMID 32121014, 2020). "In a tumor cell, chronic hypoxia does not change the expression of CCL1/I-309 as demonstrated by lung adenocarcinoma cells and hepatocellular carcinoma." (PMID 32781743, 2020). "No statistically significant main effects of tumor or interactions with time were evident for other inflammation-related genes (Il-6, Ccl5, Ccl1, Ccl22, Cx3cl1; p>0.05)." (PMID 27548621, 2016). "Gene expression analysis in pretumor mammary glands showed that all growth factors and chemokines observed to be elevated before tumor development in continuous HFD mice at 13 weeks of age (i.e., Tgfa, Ccl1, Ccl17, Ccl20, Ccl22, and Tgfb1) were elevated in LFD-HFD mammary glands at this time." (PMID 26526858, 2015). "Similarly, CXCL5, CXCL13, CCL1, CCL7 and CCL26 in WF collected from patients with T1–2 tumor tend to be higher than those with Tis, and the profiles of CXCL13, CCL27, MMP-1 and MMP-7 in WF from N1–3 patients tend to be higher than those with N0." (PMID 26313265, 2015). "Among them, the chemokine family, including CC (e.g., CCL1, CCL3, CCL5, CCL7, and CCL15), CXC (e.g., CXCL1, CXCL3, CXCL5, and CXCL10), XC (e.g., XCL1 and XCL2), and CX3C (e.g., CX3CL1), plays a pivotal role in tumor development, metastasis, and chemotherapy resistance 30-33." (PMID 40740234, 2025). "Moreover, although IL-10 (189 ± 78 pg/mL) and CCL1 (3.2 ± 1.9 ng/mL) were detected in the culture media of CD14+ cells from patients with advanced disease, the production of these cytokines was abolished after treatment and tumor regression." (PMID 32824016, 2020). "The fact that high expression of CCL1 and FoxP3 was found in high-grade tumors again suggests their detrimental effect on prognosis, although we could not find a significant effect on overall survival or tumor-free survival in our analysis." (PMID 30572845, 2018). "CCL1, but surprisingly not CCL22, showed a significant correlation with the number of tumor-infiltrating FoxP3+ Treg (p< 0.001)." (PMID 30572845, 2018). "In this study, we did not observe any significant difference of primary tumor growth and the lung metastasis in the mice receiving different inhaled anesthetics after surgery, nor in the levels of pro-inflammatory cytokines (IL-6, MCP-1, CCL-1, or VEGF)." (PMID 35222023, 2022).
infection (40 papers, 2008 to 2025). The state of being infected such as from the introduction of a foreign agent such as serum, vaccine, antigenic substance or organism. "Examination of chemokine expression at memory showed that infection resulted in sustained upregulation of transcripts encoding for a variety of different chemokines, including CCL1, CCL2, CCL5, CCL8, CXCL9 and CXCL10 compared with control flank skin from the same animals." (PMID 27160938, 2016). "The objective of the present study was to determine whether there was an association between polymorphisms of TNF, LTA, IL1B, IL6, IL8, and CCL1 and the infection and severity of the illness caused by the pandemic A/H1N1 in Mexico in 2009." (PMID 23148654, 2012). "The result showed that distal gut apoptosis was significantly lower in ∆AmoG-infected fish compared to those with CCL1 or ∆AmoG-C infections." (PMID 40006742, 2025). "The results showed that CCL1 infection led to discernible alterations in the gut microbiota compared to ΔAmoG infection, indicating that the ∆AmoG mutant exhibited a diminished ability to compromise the gut mucosal barrier." (PMID 40006742, 2025). "It is reported that the infection of microsporidia Encephalitozoon cuniculi up-regulated expression of CCL1, CCL2, CCL3, CCL7 and other chemokines." (PMID 36015036, 2022). "Mice exhibited elevated pro-inflammatory cytokines, such as CCL1, CXCL10, and CCL7, in CSF at least 7-weeks post-infection; CCL1 is associated with impairments in cognitive function." (PMID 35624923, 2022). "Concurrently, CCL1 can recruit innate immune cells (myeloid and DC lineages) to the site of infection." (PMID 34566986, 2021). "The ILC2s of Cluster 14 expressed Cor1a, Samhd1, Ccl1 (monocyte chemotaxis), Arg1 (promotes acute type 2 inflammation), and C1qbp (involved in multiple infection and inflammatory responses)." (PMID 32351546, 2020). "Accordingly, we found increased RNA abundance of Arg1, Socs1, Sra1, Saa1, Ciita, Marco, Mgl2, Cd209d, Cd209e, Cd209f, Ccl1, Ccl11, Ccl17, Ccl19, Ccl20, Ccl22, and Ccl24 genes in Stat2−/− mice when compared to WT mice during super-infection." (PMID 30337919, 2018). "The levels of CXCL1, CXCL10, CCL1, CCL3, IFN-γ, TNF-α and IL-6 were significantly increased in the lungs of RSV-infected IL-10-deficient mice compared to control mice on day 8 post infection." (PMID 22393401, 2012). "Moreover, iron levels in the serum, gut, and liver of fish infected with CCL1 and ∆AmoG-C were substantially lower than those seen after infection with ∆AmoG." (PMID 40006742, 2025). "Additionally, plasma D-lactic acid and LPS, markers of gut lining integrity, were notably lower in ΔAmoG-infected fish compared to those with CCL1 and ΔAmoG-C infections." (PMID 40006742, 2025). "CCL1 has been suggested to play a key role in host defense mechanisms, and up-regulation of CCL1 may defend against infections." (PMID 27536524, 2016). "In our model, some chemokines reported to be part of the "1st and 2nd waves" of chemokine expression by DC cells, specifically Xcl1, Cxcl9, Cxcl16, Ccl1, Ccl2, Ccl3, Ccl4, Ccl5, Ccl7 and Ccl8 are expressed at increased levels in lung i.n. samples at 3 weeks post-infection." (PMID 20942964, 2010). "Similarly, at the 48 hour timepoint, pattern "MTB" includes 288 genes whose expression levels changed preferentially after infection with mycobacteria (e.g. CCL1, ATP6V1A, IL27RA), but only 33 of these genes are in the corresponding pattern at the 18 hour timepoint." (PMID 26586179, 2015). "Before infection, the latent condition presented the chemokine panel with near-high levels of CXCL11 and mild or moderate levels of CXCL2, CCL4, CCL2, CCL1, and CXCL9." (PMID 37149713, 2023). "Following infection, expression levels of the immunomodulatory cytokines C-C motif chemokine 22 (CCL22), CCL1, IL-23α, IL-3, IL-4, matrix metalloproteinase 9 (MMP9), IL-21, C-X-C motif chemokine 2 (CXCL2), and CCL2 were increased." (PMID 28507072, 2017).
infection (continued). "Owing to the expression of chemokine receptors such as chemokine ligand 1 (CCL1), CCL18, and intercellular adhesion molecule-1 (ICAM-1) on M2-Exos, they can exhibit high recruitment of infection sites, thereby effectively solving the problem of poor targeting of existing Exos." (PMID 40177029, 2025). "We broadly confirmed a decrease in inflammatory genes, including Ccl1, Cxcl9, Tnf, and Ifnb1, among others, in infected Gsdmd−/− versus WT mice, while no baseline differences were observed in the absence of infection." (PMID 38553499, 2024). "Infection, trauma, ischemia, and toxins increase levels of proinflammatory cytokines, including TNF-α, IL-1β, IL-6, IL-18, and chemokines such as C-C motif chemokine ligand 1 (CCL1), CCL5 and C-X-C motif chemokine ligand 1 (CXCL1)." (PMID 36313229, 2022). "However, gut permeability, bacterial load, and lethality did not significantly differ between CCL1, ΔAmoG, and ΔAmoG-C infections when the Wnt/β-catenin pathway was activated." (PMID 40006742, 2025). "The receptor for CCL1 (CCR8) is expressed on specific subsets of TRM, so this mechanism could be in place to recruit TRM at other regions of the tissue to specific niches of infection." (PMID 34566986, 2021). "In addition, GM-CSF, KC and monocyte chemoattractant protein-1 (MCP-1 (C-C motif chemokine ligand (CCL1)) were detected systemically and at increased levels at 7 DPI, further indicating a systemic recruitment of inflammatory and innate immune cells to sites of infection." (PMID 33465158, 2021). "Consistent with previous findings, LCMV-infected WT mice showed a significant increase of CCL2 on day 3 postinfection and IL-5 on day 7 postinfection, only, while TNF, IL-1β, IL-6, IFN-γ, CCL1 and CCL22 levels did not change following infection." (PMID 32310998, 2020).
cancer (34 papers, 2015 to 2025). A tumor composed of atypical neoplastic, often pleomorphic cells that invade other tissues. "In CRC, Snail-expressing cancer-associated fibroblasts (CAFs) showed different cytokines secretion profiles including CCL1, CCL7, and CXCL1 when compared to normal fibroblasts affecting CRC cell migration." (PMID 38935747, 2024). "Elevated expression of CCL1 in a cancer cell occurs in leukemia caused by viruses, e.g., human T cell leukemia virus type 1 (HTLV-1)." (PMID 33076281, 2020). "In addition to the effect on a cancer cell, CCL1 causes angiogenesis on vascular endothelial cells via CCR8." (PMID 33076281, 2020). "CCL1 is a potent recruiter of regulatory T cells (Tregs) in cancer and is secreted by monocytes, macrophages, and T lymphocytes." (PMID 39409924, 2024). "ARG1 expression was the most strongly associated with IL1A, NRG1, CCL1, and CRP in cancer str of the CRC tumors among the numerous associated genes (13 401 genes)." (PMID 38557819, 2024). "Several CC chemokines, such as CCL1, CCL2, CCL5, CCL18, and CCL21, have been implicated in cancer, exhibiting both pro- and anti-tumorigenic roles." (PMID 39409924, 2024). "RIgE antibodies and CCCL5 chemokine have an anticancer role, whereas IgG4, free light chains, Il‐10, TGF‐β, lipocalin‐2, CCL1 chemokine promote cancer progression." (PMID 35344301, 2022). "This Sp1 expression in turn induces the production of CCL1 in activated LECs to recruit TAMs and cancer cells, resulting in lymphatic vessels encapsulated by TAMs (LVEM) to promote cancer metastasis." (PMID 36046433, 2021). "In cancer, CCL1 has an antiapoptotic activity and induces chemoresistance to anticancer drugs due to the activation of the ERK MAPK cascade via CCR8." (PMID 33076281, 2020). "Metastasis to lymph nodes is not only associated with the described mechanism but also with the high expression of CCL1 in a lymph node combined with the expression of CCR8 on a cancer cell." (PMID 33076281, 2020). "Furthermore, comprehensive pan-cancer analysis indicated that GPR141 expression exhibited substantial associations with numerous chemokine family members, excluding CCL1, CCL16, and CCL27." (PMID 40959105, 2025). "Additionally, the mRNA levels of Treg chemokine receptors Ccr4, Ccr8, and Ccr10 as well as their ligands, Ccl1, Ccl17, and Ccl22 are significantly upregulated in the v-rasHa/ΔNp63α carcinomas compared to v-rasHa/Stuffer tumors or normal skin." (PMID 37638000, 2023). "CCL1/CCR axis was found to be correlated with cancer-related inflammation and immune evasion." (PMID 34893045, 2021). "Yet, in another group, only receptors were significantly increased (e.g., PDGFRA and CCR8) suggesting that corresponding ligands, PDGF and CCL1, often overexpressed in cancers, may create a chemokine gradient facilitating recruitment of M-LECP." (PMID 28598999, 2017). "In addition, we analyzed the NUDT21 and chemokine, receptor, and immune activator relationships, as shown in the heat map, NUDT21 was negatively correlated with several chemokines (CCL1, 2, 3, 4, and 5), numerous receptors, and immunostimulatory agents in pan-cancer." (PMID 38349866, 2024). "Inflammatory cytokines such as IL-6, CCL-1, MCP-1, and VEGF play a vital role in cancer progression and metastasis." (PMID 35222023, 2022). "VNS treatment resulted in a significant reduction of I-309/CCL1 and MDC/CCL22, which is in line with peripheral reduction of Tregs, since both have been described to regulate Treg recruitment in murine cancer models." (PMID 34925341, 2021). "At the same time, due to the expression of CCL1 in lymph nodes, this chemokine participates in metastasis to these peripheral lymphoid organ through the CCR8 receptor on cancer cells that have entered lymphatic vessels." (PMID 33076281, 2020).
cancer (continued). "This novel approach revealed dynamic, preferential cancer cell invasion within specific anatomical regions of LNs, particularly the subcapsular sinus (SCS) and cortex, as well as chemokine-rich domains of immobilized CXCL13 and CCL1." (PMID 40109746, 2025). "Further, cancer cells can upregulate the production of CCR7/8 and CXCR4/5, which interact to the corresponding receptors from the lymph node namely CCL1/21 and CXCL10/12 respectively, resulting in the migration of cancer cells to the lymphatic vessels by chemotaxis." (PMID 38940900, 2024). "Moreover, we found that USP5 showed certain correlation with majority of chemokines with the exception of CCL1, CCL16, CCL27, CCL24 and CCL25 in pan-cancer." (PMID 37268697, 2023). "For this, it may be helpful to examine the chemokines CCL22 and CCL1 in the TME of EC, as has been reported for other cancer entities." (PMID 36098901, 2022). "Finally, CCL1 increases the expression of interleukin 6 (IL-6) in MDSC, which acts as a proinflammatory in the cancer microenvironment." (PMID 33076281, 2020). "Among several chemokines, CCL1, −2, −4, −5, −7, −8, −12, −13, and IL6 might influence the interaction of inflammation with cancer malignancy, and CCL2, −3, −5, −7, CXCL12, −14, and IL6 were found to be able to affect the macrophage infiltration." (PMID 26790618, 2016). "CCL1 could be an aggressive TAMC marker as recently shown, and fluorescent double immunostaining revealed that CCL1 with myeloid markers of CD204 were colocalized in human cancer tissues." (PMID 38557819, 2024).
inflammation (4 papers, 2016 to 2025). Aberrant reaction of the microcirculation characterized by movement of fluid and leukocytes from the blood into extravascular tissues. "Liver injury driven by CCL1/CCR8-induced monocyte infiltration-differentiation and HSCs activation cause liver inflammation-fibrosis." (PMID 40486848, 2025). "This disruption has been shown to cause a downregulation in the expression of Arntl (BMAL1), a core circadian clock gene, and leads to lung inflammation and injury through the increased release of the proinflammatory cytokines CCL1 and CXCL." (PMID 39273313, 2024). "Intriguingly, we observed that 32 targeted mRNAs were enriched in immune related functions and several mRNAs (e.g., Ccl1 and Il18r1) were related to liver inflammation and fibrosis." (PMID 31269941, 2019). "We evaluated the phenotype of these mice and the in vivo effects of CCL1 overexpression on acute and chronic lung inflammation." (PMID 27536524, 2016). "CCL1 did not play major roles in this acute lung inflammation model." (PMID 27536524, 2016).